ERCC1 (ERCC excision repair 1, endonuclease non-catalytic subunit)
Description:
[Isoform 1]: Non-catalytic component of a structure-specific DNA repair endonuclease responsible for the 5'-incision during DNA repair. Responsible, in conjunction with SLX4, for the first step in the repair of interstrand cross-links (ICL). Participates in the processing of anaphase bridge-generating DNA structures, which consist in incompletely processed DNA lesions arising during S or G2 phase, and can result in cytokinesis failure. Also required for homology-directed repair (HDR) of DNA double-strand breaks, in conjunction with SLX4. [Isoform 2]: Not functional in the nucleotide excision repair pathway. [Isoform 3]: Not functional in the nucleotide excision repair pathway. [Isoform 4]: Not functional in the nucleotide excision repair pathway.
Synonyms: RAD10; COFS4; UV20
Tractability: Small molecule: a high-quality ligand is known. PROTAC: UniProt records ubiquitination sites on it; ubiquitination databases record sites on it; its protein half-life has been measured; a small molecule that binds it is known.
Safety:
Unwanted effects reported when the protein is acted on. In parentheses: how it was acted on, where the effect was seen, and who reports it.
anemia and nephrotoxicity (source: ClinPGx)
drug toxicity (source: ClinPGx)
febrile neutropenia (source: ClinPGx)
mucositis (source: ClinPGx)
nephrotoxicity (source: ClinPGx)
neuropathy (source: ClinPGx)
neutropenia (source: ClinPGx)
no association with drug toxicity (source: ClinPGx)
side effects (source: ClinPGx)
vomiting (source: ClinPGx)
Gene: Protein-coding gene on chromosome 19 (45,407,333 to 45,478,867, reverse strand). Ensembl gene ENSG00000012061.
Subcellular location: Nucleus (Isoform 1); Cytoplasm (Isoform 2); Nucleus; Nucleus (Isoform 3); Nucleus (Isoform 4)
Subcellular location (Human Protein Atlas): Nucleoplasm
Pathways (Reactome):
DNA Repair: Dual Incision in GG-NER; Dual incision in TC-NER; Fanconi Anemia Pathway; Formation of Incision Complex in GG-NER; HDR through Single Strand Annealing (SSA)
Gene Ontology:
Molecular function: 3' overhang single-stranded DNA endodeoxyribonuclease activity; damaged DNA binding; DNA binding; protein binding; single-stranded DNA binding; single-stranded DNA endodeoxyribonuclease activity; promoter-specific chromatin binding; TFIID-class transcription factor complex binding
Biological process: DNA repair; double-strand break repair via nonhomologous end joining; mitotic recombination; negative regulation of protection from non-homologous end joining at telomere; negative regulation of telomere maintenance; nucleotide-excision repair; response to oxidative stress; telomeric DNA-containing double minutes formation; positive regulation of t-circle formation; t-circle formation; UV-damage excision repair; DNA recombination; double-strand break repair; regulation of telomere maintenance; telomere maintenance
Cellular component: chromosome, telomeric region; cytoplasm; ERCC4-ERCC1 complex; nucleoplasm; nucleotide-excision repair complex; nucleotide-excision repair factor 1 complex; nucleus
Genetic constraint (gnomAD): Loss-of-function variants: 36 observed, 36.4 expected, observed/expected ratio (o/e) 0.99, 90% interval 0.76 to 1.31. The upper end of that interval is the gene's LOEUF score, 1.31, which puts it in group 5 of 6, group 1 being the genes least tolerant of losing a copy. Missense variants: 321 observed, 366.18 expected, observed/expected ratio (o/e) 0.88, 90% interval 0.8 to 0.96. Synonymous variants: 147 observed, 154.9 expected, observed/expected ratio (o/e) 0.95, 90% interval 0.83 to 1.09.
Homologues: Orthologues: chimpanzee ERCC1 (100% identical), guinea pig ERCC1 (90% identical), macaque ERCC1 (89% identical), dog ERCC1 (88% identical), pig ERCC1 (88% identical), mouse Ercc1 (86% identical), rat Ercc1 (80% identical), zebrafish ercc1 (58% identical), tropical clawed frog ercc1 (56% identical), Drosophila melanogaster Ercc1 (40% identical), Caenorhabditis elegans ercc-1 (25% identical).
Diseases named in the same sentence as ERCC1 in open-access papers:
ERCC1 is named in the same sentence as 221 diseases in open-access papers, as found by Europe PMC text mining. Sharing a sentence is not in itself a finding about the gene and the disease. The quoted sentences say what the papers report.
lung cancer (108 papers, 2003 to 2025). A malignant neoplasm involving the lung. "This study highlights ERCC1-iASPP as a potential diagnostic and therapeutic target in smoking-related lung cancer." (PMID 41298233, 2025). "Independent studies on ERCC1‐deficient non‐small cell lung cancer cells, pancreatic cells, and tissue‐resident microglia have demonstrated that ERCC1 loss leads to an accumulation of cytoplasmic DNA fragments." (PMID 40279334, 2025). "In summary, the findings revealed that the ERCC1 rs11615 and rs3212986 polymorphisms are associated with a higher risk of lung cancer." (PMID 39431656, 2024). "For example, OPN overexpression increased PI3K, p-ERK1/2, and excision repair cross-complementation group 1 (ERCC1) expressions in lung cancer and caused cisplatin resistance, but OPN silencing decreased this effect." (PMID 39062100, 2024). "ERCC1 has been studied mainly in the field of cancer, focusing on the relationship between its polymorphisms and the development of cancers, such as lung cancer." (PMID 39283905, 2024). "For instance, ERCC1 variant rs2298881 G allele increasing the risk of lung cancer development is associated with better prognosis." (PMID 37858068, 2023). "Recent evidence investigates the association between ERCC1 mRNA expression levels and clinical findings after treatment with a combination of gemcitabine and cisplatin for patients with advanced-stage nonsmall-cell lung cancer." (PMID 37298600, 2023). "The down-regulation of ERCC1 is associated with increased chemotherapy sensitivity and increased responses to platinum-based chemotherapeutic agents in lung cancer." (PMID 35877239, 2022). "Among the SNPs associated with an increased risk of lung cancer, ERCC1 rs735482 in the recessive model was significantly related to pathological type." (PMID 35069899, 2022). "ERCC1 functions in the repair of DNA strand breaks caused by platinum-based drugs, thus conferring an increased resistance to platinum-based therapy in lung cancer." (PMID 35877239, 2022). "Here, we investigated the link between SNPs in DNA damage repair pathway genes and susceptibility to lung cancer by studying three ERCC1 and two ERCC5 SNPs in a Chinese Han population." (PMID 35069899, 2022). "At present, there are few studies on the effect of ERCC1 gene polymorphism on the quality of life of lung cancer patients." (PMID 34284736, 2021). "The purpose of this study was to assess the predictive role of particular single nucleotide polymorphisms (SNPs) in the promoter regions of TOP2A and ERCC1 genes in non‐small cell lung cancer patients (NSCLC) treated with chemotherapy." (PMID 31797573, 2020). "DNA damage or DNA repair defects caused by BRCA or ERCC1 mutations can also activate this pathway and thereby potentiate PARP inhibitor effects in ERCC1-deficient nonsmall cell lung cancer, BRCA1-deficient TNBC, and ovarian cancer." (PMID 32029455, 2020). "It has been reported that ERCC1 gene polymorphisms are associated with the risk of some cancers, such as pancreatic cancer, nasopharyngeal carcinoma, lung cancer, melanoma, childhood gastric cancer, and childhood acute lymphoblastic leukemia." (PMID 33029487, 2020). "The variant allele of rs3212961 was shown to be associated with risk of lung cancer among long-term smokers, and the ERCC1 rs735482 A allele was associated with the tumor size of hepatocellular carcinoma." (PMID 33029487, 2020). "ERCC1 rs3212986 AA genotype revealed a higher risk of lung cancer compared to CC genotype (OR = 2.061, 95%CI: 1.057‐4.017)." (PMID 30453383, 2018). "On the other hand, low ERCC1 mRNA levels in primary gastric adenocarcinoma and lung cancer showed a positive association with improved survival of patients treated with cisplatin in combination with fluorouracil or gemcitabine 21,22." (PMID 30208165, 2018). "Particularly stratified by smoking status in cases and controls, A allele of ERCC1 rs3212986 also exhibited an enhanced risk to develop lung cancer in smokers only (P < 0.05)." (PMID 30453383, 2018).
lung cancer (continued). "Zhou et al30 consistently showed that the AA genotype of ERCC1 rs3212986 polymorphism (or ERCC1 haplotypes) had significant interaction between cumulative cigarette smoking and lung cancer risk." (PMID 30453383, 2018). "PPP1R13L rs1970764, rs1005165, CD3EAP rs967591, rs735482, rs1007616, rs62109563, and ERCC1 rs3212965 were all associated with lung cancer risk in at least one of the models." (PMID 27183913, 2016). "In summary, we have fine-mapped the sub-region encompassing ERCC2, PPP1R1, CD3EAP and ERCC1 on chromosome 19q13.3 region in relation to lung cancer susceptibility among Chinese." (PMID 27183913, 2016). "ERCC1 rs3212965 [OR (95% CI) = 0.70 (0.52-0.94), P = 0.019] was associated with lowered lung cancer risk in the over-dominant model." (PMID 27183913, 2016). "Apart from those two common ERCC1 variants, associations of three other ERCC1 polymorphisms (rs3212961 (17677A>C), rs3212948 G>C, and rs2298881 C>A) with lung cancer risk have also gained increasing attentions." (PMID 24841208, 2014). "To date, four eligible studies investigating the roles of ERCC1 rs3212961 in the lung cancer risk were available." (PMID 24841208, 2014). "All studies reported the association between at least one ERCC1 polymorphism of interest and lung cancer risk." (PMID 24841208, 2014). "Characteristics of studies that explored the association between ERCC1 polymorphisms and lung cancer risk." (PMID 24841208, 2014). "Studies, inspecting the associations between multiple ERCC1 genetic variations and lung cancer risk were divided into several sub-studies, each of which encompassed the analysis of a single polymorphism." (PMID 24841208, 2014). "Recently, several meta-analyses have reported conflicting conclusion regarding to the association between the ERCC1 rs11615 polymorphism and lung cancer risk." (PMID 24841208, 2014). "The effect of ERCC1 rs3212948 polymorphism in ERCC1 gene expression was also explored since it was suggested to associate with decreased lung cancer risk." (PMID 24841208, 2014). "Association between ERCC1 rs11615 or rs3212986 polymorphism and risk of lung cancer is seemingly biologically worthy of approval, since these two polymorphisms have been thought to alter transcript stability and mRNA levels, respectively." (PMID 24841208, 2014). "Initially, the meta-analysis indicated a significant association of the ERCC1 rs11615 polymorphism with lung cancer under the homozygous model with moderate corresponding among-study heterogeneity (I2 = 22.8%, P = 0.01)." (PMID 24841208, 2014). "Pooled ORs from 11 eligible studies (8,215 cases vs. 11,402 controls) suggested a significant association of ERCC1 rs11615 with increased risk for lung cancer (homozygous: CC versus TT, OR = 1.24, 95% CI: 1.04–1.48, P = 0.02)." (PMID 24841208, 2014). "Four eligible studies with 4,653 cases and 6,921 controls were acquired for evaluating the association of another ERCC1 tagSNP rs2298881 with lung cancer." (PMID 24841208, 2014). "The putative roles of ERCC1 gene polymorphisms in lung cancer susceptibility have been widely investigated." (PMID 24841208, 2014). "Results of overall and stratified analyses for the associations of ERCC1 polymorphisms and risk of lung cancer**." (PMID 24841208, 2014). "For example, the ERCC1 Asn118Asn (rs11615) SNP has been reported to be associated with some specific subtype of lung cancer as well as early onset of lung cancer." (PMID 23166636, 2012). "As such, low expression levels of ERCC1 have been implicated in lung cancer susceptibility and tumorigenesis, whereas high expression levels are associated with favorable overall prognosis." (PMID 22629454, 2012). "The excision repair cross complementation group 1 (ERCC1) is deficient in some lung cancers, and patients with deficient tumors are more sensitive to cisplatin-based therapy than tumors with sufficient ERCC1." (PMID 21679440, 2011).
lung cancer (continued). "Several independent studies, each an order of magnitude greater than most published series, are required to allow accurate estimation of the true associations between ERCC1 expression and outcomes in lung cancer patients, particularly in SCLC." (PMID 22022380, 2011). "Various studies in colorectal cancer and lung cancer patients suggest that the ERCC1 118CC genotype is associated with longer OS and a better response towards platinum agents." (PMID 19536092, 2009). "To date, only a few studies have examined the relationship between ERCC1 polymorphism and survival of lung cancer, and they didn't control the influence of gender, smoking status and histopathologic subtypes." (PMID 20003463, 2009). "In terms of chemotherapy response, a few studies suggested an association between ERCC1 Asn118Asn polymorphism and response to platinum-based treatment of lung cancer." (PMID 20003463, 2009). "Using immunohistochemistry in resected tumors from patients included in the International Adjuvant Lung Cancer Trial, the study of important biomarkers showed that high ERCC1 protein expression was associated with improved survival in chemo-naïve patients." (PMID 19578506, 2008). "For colorectal and lung cancer patients the mRNA levels and the expression of the ERCC1 protein are associated with the response to platinum-based chemotherapeutic drugs with direct impact on cancer patient survival." (PMID 18289367, 2008). "Previous studies have found that ERCC1 rs3212986 is a genetic susceptibility factor for lung cancer and is associated with a reduced overall survival rate in patients with late-stage non-small cell lung cancer and decreased activity of the chemotherapy drug cisplatin." (PMID 39283905, 2024). "Finally, further experiments are needed to elucidate the specific contribution of ERCC1 polymorphisms to the susceptibility to lung cancer susceptibility as well as to reveal other functional SNPs involved in DNA repair pathways." (PMID 39431656, 2024). "ERCC1 rs11615 and rs3212986 polymorphisms are associated with a higher risk of lung cancer." (PMID 39431656, 2024). "ERCC2 rs13181 and ERCC1 rs3212986 SNPs have an elevated association with lung cancer risk 2, 11, while the O6-methylguanine-DNA methyltransferase gene SNP rs12917 is associated with an increased risk of lung cancer." (PMID 35069899, 2022). "An example is the known sensitivity of ERCC1-deficient lung cancer cells to PARPis such as Npb." (PMID 29423093, 2018). "For example, ERCC1 C118T was associated with lung cancer risk." (PMID 28924212, 2017). "Interestingly, reduced expression of NR1I2 has also been shown to increase the risk of lung cancer, consistent with an important role for this TF in the normal expression of ERCC1." (PMID 28100260, 2017). "An updated meta-analysis was conducted to explore whether lung cancer risk could be attributed to the following ERCC1 polymorphisms: rs11615 (T>C), rs3212986 (C>A), rs3212961 (A>C), rs3212948 (G>C), rs2298881 (C>A)." (PMID 24841208, 2014). "Polymorphisms in ERCC1 gene affect mRNA expression and have received much attention as potential predictors of cisplatin and platinum adjuvant therapy outcome, and patient prognosis in lung cancer, melanoma, bladder cancer, in addition to esophageal cancer." (PMID 25191856, 2014). "The current meta-analysis examined whether five most commonly studied ERCC1 polymorphisms (rs11615, rs3212986, rs3212961, rs3212948, and rs2298881) were associated with lung cancer risk." (PMID 24841208, 2014).
lung cancer (continued). "Therefore, we conducted this updated meta-analysis to reassess the associations of the first two common polymorphisms in the ERCC1 gene and lung cancer risk, and explore the influence of the other three polymorphisms on predisposition to lung cancer." (PMID 24841208, 2014). "Likewise, the ERCC1 19007 C (rs11615) allele was found to be associated with an elevated lung cancer risk in Asian populations." (PMID 23166636, 2012). "The level of response may be related to the ERCC1 Asn118Asn polymorphism, and the ERCC1 C8092A polymorphism as well, for lung cancer patients." (PMID 18289367, 2008). "For the ERCC1 gene, the defective ERCC1 gene could increase the incidence of vascular diseases, and genetic polymorphisms of ERCC1 could affect the efficiency of chemotherapy, as well as the susceptibility of a variety of diseases, including lung cancer and several cardiovascular diseases." (PMID 35627777, 2022). "It remains to be further studied how ERCC1 could affect mutations of the EGFR gene in lung cancer." (PMID 23940741, 2013). "The frequencies of CC, TC, and TT genotypes at the rs11615 of the ERCC1 gene were 36.14%, 53.01%, and 10.840% in lung cancer patients, as well as 32.77%, 64.70%, and 2.52% in the control group." (PMID 39431656, 2024). "The frequencies of CC, AC, and CC genotypes at the rs3212986 of the ERCC1 gene were 38.55%, 43.37%, and 60.24% in lung cancer patients, as well as 45.37%, 46.21%, and 8.40% in the control group." (PMID 39431656, 2024). "It has been reported in studies that ERCC1 expression level differences cause platinum resistance in cell lines in ovarian, cervical, testicular, bladder, and non-small-cell (NSCLC) lung cancers." (PMID 37895364, 2023). "The expression of ERCC1 protein is a main predictor of the benefit of cisplatin-based chemotherapy in lung cancer, and its gene contains AP-1 sites bound by the transcription factors JUN and ATF2." (PMID 37686122, 2023). "ERCC1 Expression in Lung Cancer: Excision repair cross-complementation group 1 (ERCC1) expression levels in NSCLC have been explored as a predictive biomarker for response to platinum-based chemotherapy." (PMID 38202898, 2023). "In the present study, we have described in detail of some of the miRNAs or lncRNAs that can be used as therapeutic tools to alter the expression of ERCC1 and reverse back the cisplatin sensitivity in lung cancer cells." (PMID 36778005, 2023). "Multivariable logistic regression was used to investigate the association of ERCC1 and ERCC5 SNPs with lung cancer risk." (PMID 35069899, 2022). "Haplotype-base risk prediction of SNPs in ERCC1 and ERCC5 genes for lung cancer was performed using the HaploView." (PMID 35069899, 2022). "Both ERCC1 and ERCC2 haplotypes are associated with multiple domains of quality of life in lung cancer patients." (PMID 34284736, 2021). "Both ERCC1 and ERCC2 have SNP loci associated with quality of life, anxiety and depression in lung cancer, mainly focusing on ERCC1rs11615 and rs3212986, associated with multiple domains of quality of life." (PMID 34284736, 2021). "There are few studies on the relationship between single nucleotide polymorphisms (SNPs) of ERCC1 and ERCC2 and QoL in lung cancer patients." (PMID 34284736, 2021). "According to the results, emodin has a certain effect on ERCC1 expression in lung cancer cell lines and has been reported to increase the cytotoxic effects induced by siRNA transfection." (PMID 34073059, 2021). "Studies have shown that the activity of the ERCC1‐XPF complex can reflect the efficiency of NER, and the ERCC1‐XPF complex repairs DNA DSBs via HR, thus, causing cisplatin resistance in lung cancer." (PMID 34766149, 2021). "For example, lung cancer patients with high ERCC1 expression have significantly longer overall survival than those with low ERCC1 expression." (PMID 33936178, 2021).